CUL5 (cullin 5)
Diseases named in the same sentence as CUL5 in open-access papers (continued):
Sharing a sentence is not in itself a finding about the gene and the disease.
tumor (29 papers, 2015 to 2026). "Collectively, APC11 deficiency promotes cell migration in vitro and tumor metastasis in vivo by disrupting CUL5‐mediated degradation of integrin β1." (PMID 41159544, 2026). "Of note, several negative regulators of anti-tumor responses were down-regulated in CUL5 KO cells including exhaustion-associated biomarkers (NR4A2, PDCD1 and CD160), myeloid-derived suppressive cell promoting cytokine CSF2, and pro-apoptosis factor BCL2L11." (PMID 38242867, 2024). "Combining the GEPIA2 tool with TCGA tumor expression data revealed the top 100 genes associated with CUL5 expression." (PMID 34415831, 2021). "CUL5 has previously been implicated to function as a tumor suppressor by regulating cellular proliferation." (PMID 30631037, 2019). "In the present report, we show that a reduced CUL5 gene expression or CUL5 deletion is associated with significantly impaired overall survival in ccRCC patients and with more rapid tumor progression, respectively." (PMID 30631037, 2019). "Advanced age (higher than median), high grade, metastasis at diagnosis (M+), high tumor stage and low CUL5 expression were independently associated with poor survival in ccRCC patients by being present in the final step of the multivariate Cox model." (PMID 30631037, 2019). "Remarkably, low CUL5 expression was an independent prognostic factor in ccRCC, a tumor entity for which patient risk stratifiers are urgently needed." (PMID 30631037, 2019). "We hypothesized that CUL5 mutation alters its expression level, alters the body’s immune system, alters the expression of various immune cells, influences tumor prognosis and survival time, and affects some pathways in vivo." (PMID 34415831, 2021). "We hypothesized that CUL5 mutation alters its expression level, causes changes in the body’s immune system, changes the expression levels of various immune cells, and further influences tumor prognosis and survival time, affecting some pathways in vivo." (PMID 34415831, 2021). "These dual functions of CUL5 appear contradictory: on one hand, it exhibits tumor‐suppressive characteristics by maintaining genome stability; on the other hand, it displays oncogenic behavior by reducing sensitivity to chemotherapeutic agents." (PMID 41159544, 2026). "Transcriptomic profiling of TCGA datasets revealed significant up-regulation of CUL1, CUL2, CUL4A, CUL4B, CUL5, CUL7, and CUL9 in tumor tissues, with higher expression correlating with advanced stage and poorer survival, particularly for CUL5 and CUL7." (PMID 42021323, 2026). "This article summarizes the multidimensional role of CUL5 in tumor cell therapy and prospects its potential as a novel therapeutic target in combined therapies and precision medicine." (PMID 42078440, 2026). "T cell anti-tumor activity is increased when CUL5 is deleted in CD8+ T cells, leading to an elevation of JAK/STAT and TCR signaling." (PMID 39223632, 2024). "Knocking out CUL5 in mouse CD8+ T cells significantly improves their tumor growth inhibiting ability, with significant proteomic alterations that broadly enhance TCR and cytokine signaling and their effector functions." (PMID 38242867, 2024). "Further analysis of tumor-infiltrating transferred T cells as well as those in TDLNs at the end point revealed that the CUL5 KO T cells had significantly higher IL7R and GZMB expression levels than the NC cells." (PMID 38242867, 2024). "Cul5, Ube2f and Rnf19b were top three hits in both tumor and spleen, while Zgpat, Athl1 and Cisd2 were top three hits in TDLN." (PMID 38242867, 2024). "Concordantly, the CUL5 KO group had a significantly higher number of tumor-infiltrating transferred T cells that were still capable of producing IFNg and/or TNFa upon in vitro re-stimulation than the NC group." (PMID 38242867, 2024). "The CUL5 KO T cells showed significantly stronger tumor control ability than the NC T cells, resulting in significantly improved survival." (PMID 38242867, 2024).
tumor (continued). "We also noticed that several co-inhibitory checkpoint molecules increased along with the enhanced anti-tumor functions of CUL5 KO cells." (PMID 38242867, 2024). "Other tumor-infiltrated immune cell types, including Treg cells, macrophages and NK cells showed little differences between CUL5 KO and NC, suggesting the improved therapeutic effect of CUL5 KO CD8+ T cells is largely due to transferred T cells." (PMID 38242867, 2024). "Our stepwise screening strategy combining specific selection pressures with high confident coverages described in this study allowed identification of new hits including CUL5 that are important for signaling and anti-tumor activities of CD8+ T cells." (PMID 38242867, 2024). "The marked increase in CTLA4 expression in activated CUL5 KO CD8+ T cells, on the other hand, should suppress CUL5 KO CD8+ T cells by B7-expressing cells in tumor." (PMID 38242867, 2024). "We used TCGA cohort to analyze different tumor samples and their genetic alteration status with CUL5." (PMID 34415831, 2021). "CUL5 was correlated with multiple immune cells in different tumor environments, suggesting that CUL5 affects the tumor microenvironment, progression, and prognosis." (PMID 34415831, 2021). "Our TCGA database analysis indicated that CUL5 expression was significantly higher in BRCA tumor tissues than in normal tissues." (PMID 34415831, 2021). "There was also an increase of cells with >4N DNA content, indicating the presence of polyploid/aneuploid tumor cells following CUL5 depletion." (PMID 30631037, 2019). "Taken together, our results demonstrate that CUL5 is a novel candidate tumor suppressor in ccRCC that is involved in the maintenance of genome stability and has independent prognostic value in ccRCC patients." (PMID 30631037, 2019). "In conclusion, our results indicate that CUL5 functions as a novel tumor suppressor with prognostic relevance in ccRCC and is critically involved in the maintenance of genome stability." (PMID 30631037, 2019). "CUL5 was previously reported to regulate cellular proliferation and to act as a potential tumor suppressor." (PMID 29746508, 2018). "Many publications suggested CUL5 to function as a tumour suppressor, for example, through inhibition of Src‐dependent tumorigenesis." (PMID 27239439, 2016). "Finally, in an in vivo xenograft tumor model, CUL5 knockdown significantly enhanced the tumor‐suppressive effect of paclitaxel, as reflected in reduced tumor volume and weight." (PMID 41159544, 2026). "Moreover, in adoptive cell therapies (e.g., CAR-T, TCR-T, CAR-NK), modulation of CUL5 expression can significantly enhance immune-cell proliferation, cytokine secretion, and anti-tumor efficacy." (PMID 42078440, 2026). "Notably, CUL5 exhibits dual regulatory functions in various cancers, and its expression level correlates differently with prognosis depending on tumor type." (PMID 42078440, 2026). "Indeed, CTLA4/CUL5 DKO in CD8+ T cells showed further improved tumor control in vivo compared to CUL5 KO alone." (PMID 38242867, 2024). "Ctla4 KO alone showed similar ability in tumor control to CUL5 KO." (PMID 38242867, 2024). "However, as anticipated, CTLA4 and CUL5 DKO showed a superior anti-tumor ability compared to either CTLA4 KO or CUL5 KO alone." (PMID 38242867, 2024). "Additionally, CTLA4 is markedly upregulated by CUL5 knockout, and its inactivation further enhances the anti-tumor effect of CUL5 KO." (PMID 38242867, 2024). "Taken together, our step-wise CRISPR KO screens revealed CUL5 may play an important role in regulating the persistence and effector functions of tumor-reactive CD8+ T cells." (PMID 38242867, 2024). "Novel effects of CUL5 on tumor prognosis and immune microenvironment have been revealed." (PMID 34415831, 2021).
tumor (continued). "It remains to be studied whether complexing of CUL5 with the nuclear αvβ3 participates in its turnover and tumor-promoting actions." (PMID 32728020, 2020). "Herein, we show that CUL5 is a novel candidate tumor suppressor in ccRCC." (PMID 30631037, 2019). "It is hence possible that downregulation or loss of CUL5 in ccRCC may further fuel neo-angiogenesis, which plays a central role in ccRCC driven by VHL loss, thus promoting tumor progression." (PMID 30631037, 2019). "Therefore, we reasoned that knockout of CTLA4 in combination of CUL5 KO may further release the cytotoxic power of anti-tumor CD8+ T cells." (PMID 38242867, 2024). "The present finding indicates that CUL5 expression may regulate tumor prognosis by altering and regulating certain immune cells, which has positive relationships with Tcm and Th cells, and Tgd, and negative relationships with pDC, NK CD56bright cells and NK CD56dim cells." (PMID 34415831, 2021). "Overall, our findings highlight the widespread up-regulation and functional significance of Cullin genes in CRC, with CUL5 and CUL7 emerging as key contributors to tumor progression and potential biomarkers or therapeutic targets." (PMID 42021323, 2026). "Here authors identify Cul5, a ubiquitin E3 ligase as an important inhibitor of CD8 + T cell anti-tumour cytotoxicity and persistence via involvement with both T cell receptor and cytokine-regulated central pathways." (PMID 38242867, 2024). "This approach allows us to robustly identify gene targets, including CUL5, in CD8+ T cells that regulate anti-tumor efficacy." (PMID 38242867, 2024). "To this end, in the same E.G7-OVA tumor model, we compared the anti-tumor effects of NC, CTLA4 KO, CUL5 KO and CTLA4/CUL5 double KO (DKO) OT-I T cells post adoptive transfer." (PMID 38242867, 2024). "IFN-γ increases CUL5 expression and diminishes both Cdc37 and Hsp90 from HER2 receptor, resulting in less surface HER2, further tumor senescence, and repressed tumor growth." (PMID 37174034, 2023). "For instance, CUL5 is responsible for IFN-gamma–induced proteasomal degradation of HER2 in BC, resulting in diminished cell growth and tumor senescence." (PMID 36212422, 2022). "Among the significantly enriched guide RNAs were known tumor suppressors KEAP1 and FBXW7 as well as several members of the Cullin 5 (CUL5)-RING E3 ligase (CRL5) complex, a previously undescribed mechanism of resistance." (PMID 34944063, 2021). "CUL5 expression in KIRC tumors was particularly lower than normal, and was significantly related to tumor prognosis." (PMID 34415831, 2021). "Moreover, gossypol, a natural compound derived from cottonseed, hinders the neddylation of CUL1 and CUL5 by directly binding to the RBX1-CUL1 or SAG-CUL5 complex, contributing to NOXA and MCL1 accumulation and tumor growth inhibition." (PMID 41540013, 2026). "Despite the limitations (low patient number and CUL5 expression not limited to CD8 T cells) of the TIDE analysis, the correlations are consistent with our data showing CUL5 plays important roles in CD8 cell activation and tumor killing functions." (PMID 38242867, 2024). "The molecular basis of this effect was investigated, and we now know that the Th1 cytokine IFN-γ increased E3 ubiquitin ligase Cullin-5, which led to ubiquitination and degradation of surface HER2 receptors, translating into tumor senescence and diminished tumor growth." (PMID 34899753, 2021). "The specificity of the thalidomide effect is further underscored by our observation that PMA (phorbol myristate acetate, or 12-0-tetradecanoyl-phorbol-13-acetate) (10 nM) a tumor-promoting ester treatment attenuated CUL5 but not NEDD8 signal intensity." (PMID 29746508, 2018). "Our data suggest that an up‐regulation of CUL5 not necessarily maintains tumour growth rather than EBV transmission and spread within NKTL tissues." (PMID 27239439, 2016).
tumor (continued). "The CUL5 protein was significantly upregulated upon TCR stimulation, and its KO in CD8+ T cells significantly enhanced their effector function, TCR and cytokine signaling, stemness, and survival accompanied with improved tumor control ability in vitro and in vivo." (PMID 38242867, 2024). "To further investigate the effects of CUL5 KO on primary CD8 T cell responses, we generated CUL5 KO CD8+ T cells using cells isolated from the spleens of the Cas9/OT-I mice, and performed cytokine-induced differentiation, TCR-dependent activation, and tumor cell killing assays in vitro." (PMID 38242867, 2024). "Although CUL5 protein is found downregulated in multiple cancers, the exact function of each CRL5 E3 ligase complex in oncogenesis is very diverse since CRL5 E3 ligases could promote the degradation of both oncoproteins and tumor suppressors." (PMID 34164402, 2021).
cancer (19 papers, 2005 to 2026). A tumor composed of atypical neoplastic, often pleomorphic cells that invade other tissues. "CUL5 loss delays mitotic exit, induces aneuploidy, and sensitizes cancer cells to the microtubule‐targeting drug paclitaxel by destabilizing APC11." (PMID 41159544, 2026). "UBE2F specifically interacts with RAX2/SAG to promote the neddylation of CUL5 and then mediates ubiquitination and degradation of cancer-associated proteins, including DIRAS2 and NOXA." (PMID 40290125, 2025). "Many cancers reduce CUL5 levels, and the prognosis of certain cancers is vitally linked with CUL5 expression." (PMID 34415831, 2021). "Other research groups have suggested a functional association between the multifunctional CUL5 protein and the occurrence of ovarian, lung, and breast cancers." (PMID 34415831, 2021). "It is therefore necessary to further investigate the diagnostic and therapeutic value of CUL5 in a variety of human cancers." (PMID 34415831, 2021). "We also detected that different types of cancers had potential associations between clinical survival prognosis and CUL5 gene alteration." (PMID 34415831, 2021). "High antigen KI-67 and CUL5 expression levels in tissues are associated with cancers." (PMID 32046176, 2020). "APC11 silencing promoted cancer cell migration through a mechanism dependent on its interaction with CUL5 and the resulting accumulation of integrin β1." (PMID 41159544, 2026). "This review systematically elaborates the context-dependent role, molecular regulatory network, and therapeutic targeting potential of CUL5-mediated ubiquitination in cancer cell therapy." (PMID 42078440, 2026). "The current evidence from animal and cell studies supports correlations between different cancer types and CUL5." (PMID 34415831, 2021). "Using the GEPIA2 ‘Pathological Stage Plot’ module identified correlations between cancer pathological stages and CUL5 expression including KIRC (P < 0.01) and THCA (P < 0.05), but not others (P > 0.05)." (PMID 34415831, 2021). "We therefore investigated the oncogenic role of CUL5 in 33 tumors from the Gene Expression Omnibus and The Cancer Genome Atlas databases." (PMID 34415831, 2021). "In order to determine the effects of CUL5 on cancer in humans, we used the TIMER2 website to explore CUL5 expression in various types of cancer from TCGA." (PMID 34415831, 2021). "As the first study to perform a pan-cancer analysis of CUL5, the present findings will improve the understanding of the oncogenic role of CUL5 in different tumors." (PMID 34415831, 2021). "The present study is the first to use TCGA database and the GEO project to conduct a pan-cancer investigation of CUL5." (PMID 34415831, 2021). "This is the first research study to systematically evaluate the potential role of CUL5 in disease progression and prognosis in several types of cancer." (PMID 34415831, 2021). "Patients with chromosomal deletions in the CUL5 locus showed a significantly impaired cancer-specific survival (median of 2.7 years compared to 6.5 years, p = 0.0012)." (PMID 30631037, 2019). "Therefore, maintaining the precise levels of both CUL5 and APC11 is critical for protein quality control, while deregulation of these proteins is linked to cancer metastasis and altered chemosensitivity." (PMID 41159544, 2026). "Cancer cases were divided into high- and low-CUL5 expression groups, and TCGA and GEO data were mainly used, respectively, to investigate the correlations between CUL5 expression and the prognoses of different tumors." (PMID 34415831, 2021). "In this study we used the XCELL, CIBERSORT, CIBERSORT-ABS, TIMER, QUANTISEQ, EPIC, and MCPCOUNTER algorithms to investigate various cancer types from TCGA in order to identify potential relationships between CUL5 expression and the infiltration levels of different immune cells." (PMID 34415831, 2021).
cancer (continued). "There is some evidence supporting an association between Cullin-5 (CUL5) and cancer, but no research using pan-cancer analysis has been conducted previously." (PMID 34415831, 2021). "Many aspects such as survival condition, gene expression, immune infiltration, genetic changes, and related cellular pathways are summarized in order to determine the possible molecular mechanisms of CUL5 in clinical prognoses or the pathogenesis of different cancers." (PMID 34415831, 2021). "A few reports have implicated genetic alterations in CUL5 in cancer progression and our unbiased screens reveal that the CUL5-RNF7-UBE2F ubiquitin ligase can modulate the apoptotic threshold of LK2 cells in response to multiple emerging cancer therapeutics." (PMID 31294695, 2019). "Indeed, previous work has shown that silencing CUL5 expression reduced the sensitivity of several cancer cell types to three structurally distinct inhibitors of HSP90." (PMID 29746508, 2018). "The low expression or loss of CUL5 may also explain resistance in cancers not sensitive to thalidomide." (PMID 29746508, 2018). "Similar to how APC11 depletion promotes cancer metastasis by inhibiting CRL5 activity and leading to the accumulation of integrin β1, CUL5 knockdown destabilizes APC11, thereby impairing APC/C‐associated processes." (PMID 41159544, 2026). "In several human cancer cell lines, gossypol has been found to block the neddylation of cullin enzymes (CUL5 and CUL1) by directly binding to the SAG-CUL5 or RBX1-CUL1 complex." (PMID 38098026, 2023). "As the core scaffold protein of the Cullin-RING ligase 5 (CRL5) complex, CUL5 regulates the stability of multiple substrate proteins through the ubiquitin-proteasome system (UPS), playing a crucial role in the initiation, progression, and cellular therapy of malignant tumors." (PMID 42078440, 2026). "The most frequently amplified genes across the pan-cancer atlas were BRIP1 (HDR, 8.04%), POLB (BER, 6.54%), MUS81 (HDR, 6.42%), NBN (HDR, 6.31%), and EXO1 (MMR, 6.26%), while the most frequently deleted genes were BRCA2 (HDR, 6.44%), XRCC2 (HDR, 6.38%), and CUL5 (NER, 6,28%)." (PMID 36081518, 2022).
inflammation (2 papers, 2022 to 2023). Aberrant reaction of the microcirculation characterized by movement of fluid and leukocytes from the blood into extravascular tissues. "Having determined that Cul5 deficiency in CD4+ T cells predisposes mice to Th9-mediated lung inflammation, we next wanted to assess how Cul5 functions in CD4+ T cells." (PMID 35589717, 2022). "During endotoxin-induced acute lung injury, Cul-5 was found to be necessary for pulmonary inflammation, since the levels of IL-1β, IL-6, TNF-α, CXCL1, and monocyte chemotactic protein-1 (MCP-1) were lower in the lung tissue from Cul-5+/− mice, as compared to wild-type control." (PMID 38434245, 2023).